LEP (leptin)
Diseases named in the same sentence as LEP in open-access papers (continued):
Sharing a sentence is not in itself a finding about the gene and the disease.
Insulin resistance (continued). "In multivariate logistic regression analyses, serum leptin (odds ratio:1.68, 95% confidential interval:1.08–2.63, p = 0.02) was associated with normal weight insulin resistance independently of macrosomia, free fatty acids, triglycerides, remnant-like particle cholesterol and resting pulse rate." (PMID 37217782, 2023). "In addition to that, MKX but not COBL expression showed an inverse and BMI SDS-independent association with serum leptin levels (Radjusted = −0.168, padjusted = 0.028) and the insulin resistance marker HOMA-IR (Radjusted = −0.211, padjusted = 0.003)." (PMID 36834493, 2023). "Under physiological conditions, leptin improves hepatic insulin sensitivity, suppresses glucose production, and increases peripheral glucose uptake, whereas hyperleptinemia or leptin deficiency is usually associated with hyperglycemia and insulin resistance." (PMID 38203600, 2023). "Epigenetic mechanisms such as the methylation of DNA are reported to be involved in the prenatal development of leptin and insulin resistance and these mechanisms may explain the risk of T2DM for subsequent generations." (PMID 36674935, 2023). "Interestingly, in the present study, we observed that the leptin/adiponectin ratio was positively associated with insulin resistance, as well as with body fat, visceral fat, and insulinemia." (PMID 38063544, 2023). "The inverse relationship between leptin and the Matsuda index in the pregnant bariatric cohort also corresponds well with this thesis since lower phase angle levels have been associated with insulin resistance." (PMID 37299461, 2023). "Excess visceral adiposity is associated with altered secretion of bioactive peptides like adiponectin, leptin, interleukin-6, and tumor necrosis factor-α, predisposing to inappropriate inflammatory responses, insulin resistance, increased sympathetic activity and RAAS activation." (PMID 36973671, 2023). "Leptin-deficient ob/ob mice have an increase in enzymes involved in lipid anabolism in skeletal muscle, providing evidence against reduced fatty acid oxidation in lipid-induced insulin resistance and showing a phenotype of “slow fiber type”." (PMID 36674935, 2023). "Additionally, the presence of MAFLD showed a significant correlation with adipocytokines associated with insulin resistance, such as adiponectin, leptin, and retinol-binding protein-4 (RBP-4) levels (all p < 0.001)." (PMID 37854195, 2023). "Therefore, CRP deficiency raises the efficacy that central leptin controls hepatic glucose flux and improve hepatic insulin resistance induced by lipid infusion." (PMID 37660067, 2023). "For obese patients, elevated adiponectin, leptin, and resistin may increase the risk of kidney cancer through their demonstrated effects on inflammation, insulin resistance, cell growth, and proliferation." (PMID 36069056, 2023). "Importantly, leptin levels show strong correlations with inflammation and insulin resistance, both of which are recognized risk factors for the development of CKD." (PMID 38139229, 2023). "Besides dyslipidemia, adipose tissue also has a major role in the pathogenesis of insulin resistance, which is associated with the secretion of adipokines, especially adiponectin and leptin." (PMID 38004234, 2023). "Moreover, it has been observed that high UPF intake is connected to high leptin levels, which are linked to insulin resistance." (PMID 37627527, 2023). "is positively associated with a higher high-density lipoprotein cholesterol level but negatively associated with fat mass, adipocyte diameter, insulin resistance, levels of leptin and insulin, therefore could be associated with better health." (PMID 36079824, 2022). "Last, even though the ZDF rat model shares a number of common metabolic disturbances (leptin signaling deficiency, insulin resistance, hyperglycemia, and hyperinsulinemia) with patient populations, it lacks the increased BMD and bone cortical porosity characteristic of patients with T2DM." (PMID 35742976, 2022).
Insulin resistance (continued). "Besides adiponectin, Citrus seems to act reducing other adipocytokines, as leptin and resistin, which regulate the appetite and glucose metabolism and have been associated with insulin resistance." (PMID 35237168, 2022). "Moreover, as hormones expressed in adipose tissue, adiponectin, leptin, and resistin were all closely associated with insulin resistance." (PMID 36277708, 2022). "Inhibition of NF-kB activation improved insulin resistance in leptin-deficient obese mouse models." (PMID 36145139, 2022). "Furthermore, downregulation of miR-107 has been reported in the livers of leptin-deficient and diet-induced obese mice, resulting in insulin resistance." (PMID 35409056, 2022). "However, high circulating leptin levels in obese individuals were mainly caused by leptin resistance, which was associated with increased insulin resistance." (PMID 35548430, 2022). "To date, the mechanisms underlying the potential protective role of CRP and leptin-to-adiponectin ratio (a suggested surrogate marker of insulin resistance) in breast carcinogenesis among premenopausal women are unclear and should be explored in experimental studies." (PMID 35430795, 2022). "Insulin resistance caused insufficient leptin secretion, and the leptin content in the I group and J + I group was significantly lower than that in the CK group, and this significantly affected the fat anabolism in the liver, resulting in a significant increase in triglyceride content." (PMID 36615827, 2022). "It has been stated that the increased level of insulin, which is common in type 2 DM due to insulin resistance, causes leptin overproduction, which in turn, increases leptin concentration, is related to the risk of incidence and progression of endometrial and ovarian cancers." (PMID 34751020, 2022). "The SIDD and SIRD groups with low leptin levels and characterized by insulin deficiency or insulin resistance under the precise stratification may be appropriate for leptin therapy." (PMID 34996484, 2022). "Reduced leptin sensitivity can result in the accumulation of excess triglycerides in the adipose tissue, liver, muscle, and pancreas, causing impaired insulin sensitivity and secretion and eventually insulin resistance." (PMID 35355566, 2022). "The association of visceral obesity associated HPT axis dysregulation is dependent on insulin resistance, increased serum leptin and triglycerides, reduced high density lipoprotein (HDL), the presence of hypertension, and non-alcoholic fatty liver disease (NAFLD)." (PMID 35834069, 2022). "Furthermore, knockdown of ADRP expression in the liver of leptin-deficient mice relieves hepatosteatosis and improves whole-body insulin resistance." (PMID 35432557, 2022). "It has been suggested that overnutrition/HFD activates astrocytes and microglia to release cytokines, and these cytokines then mediate inflammation in POMC and AgRP neurons and cause leptin and insulin resistance, resulting in impaired metabolism and weight gain." (PMID 36188456, 2022). "In addition, the serum leptin concentration has shown a strong positive association with insulin resistance." (PMID 35355566, 2022). "High leptin levels are closely associated with high body fat mass and may lead to further weight gain and therefore the development of insulin resistance." (PMID 36248900, 2022). "Insulin resistance which was associated with high circulating levels of IL-12, leptin, and IL-1β could be the most possible reason behind anti-TB immunity." (PMID 35832818, 2022). "Prospective studies illustrate the link between the downregulation of adiponectin as well as anti-inflammatory cytokines (e.g., IL-4 and IL-10) and the upregulation of leptin as well as proinflammatory cytokines implicated in insulin resistance (e.g., IL-6 and TNF-α)." (PMID 35329840, 2022).
Insulin resistance (continued). "Given that SIDD and SIRD groups with low leptin levels featured insulin deficiency and insulin resistance, respectively, individuals classified into these two groups may benefit from leptin replacement therapy." (PMID 34996484, 2022). "Insulin resistance, for instance, has been often associated with the leptin-to-adiponectin ratio." (PMID 36554976, 2022). "Particularly, pharmacologic or genetic induction of ER stress in the hypothalamus can mimic metabolic inflammation to cause central leptin and insulin resistance, resulting in a broad range of metabolic disorders including overeating, glucose intolerance, and hypertension." (PMID 35103058, 2022). "Specifically, insufficient sleep duration causes insulin resistance, reduced β-cell activity, and an increased caloric intake because of dysregulations in the neuroendocrine system, such as decreased leptin, increased ghrelin, and decreased sympathetic activity." (PMID 36142103, 2022). "Moreover, depletion of CD8 memory T lymphocytes is observed, together with a decreased number and function of CD4+ T lymphocytes and increased number of regulatory T cells (Treg), possibly caused by leptin and insulin resistance." (PMID 35062740, 2022). "This fact generates a greater stress condition, which in turn causes activation of the hypothalamic pituitary axis with greater cortisol release, which can promote higher insulin resistance, weight gain caused by hormonal imbalance with increased ghrelin production and reduction of leptin." (PMID 35584413, 2022). "Additionally, high leptin concentrations were also significantly associated with increased insulin resistance assessed by HOMA-IR." (PMID 36675692, 2022). "Furthermore, LEP has pro-inflammatory activity, and its elevated levels are associated with insulin resistance and liver fibrosis in obese individuals." (PMID 36501080, 2022). "Furthermore, altered endocrine function of fat tissue develops insulin resistance-related pathogenesis: levels of leptin and adiponectin are associated positively and negatively, respectively, with the severity of NAFLD." (PMID 35326230, 2022). "Our finding is also consistent with previous research which indicated that there is a significantly positive association between leptin and somatic depressive symptoms after adjusting for relevant confounding factors such as age, gender, BMI, insulin resistance, and inflammatory factors." (PMID 35911226, 2022). "In addition, leptin and adiponectin, which are secreted from adipocytes, are also associated with insulin resistance." (PMID 35056765, 2022). "Thus, our study aimed to investigate the impact of G2548A polymorphism on serum leptin levels and insulin resistance among Malaysian T2DM patients." (PMID 36381191, 2022). "Leptin is an adipokine that regulates food intake by suppressing appetite, and increased serum levels are associated with inflammation, oxidative stress, and the development of insulin resistance." (PMID 35703718, 2022). "The results of mediation analysis showed that hyperleptinemia could induce insulin resistance, and Fetuin B partially mediated the increase in insulin resistance caused by leptin." (PMID 35896788, 2022). "As a clinical recommendation, leptin levels can be considered as an ideal diagnostic tool and marker for insulin resistance and metabolic syndrome in both genders, but leptin levels could serve as an appropriate marker for detecting cancer in females." (PMID 35628271, 2022). "Moreover, leptin is associated with insulin resistance and demonstrated as a significant independent predictor of coronary artery calcification." (PMID 34093426, 2021). "However, leptin therapy has been actively used in patients with lipodystrophy, a disorder characterized by fat loss, severe insulin resistance, and NAFLD and steatohepatitis (NASH)." (PMID 33935782, 2021).
Insulin resistance (continued). "This may be due to its effects on weight loss, in addition to decreasing insulin resistance and a favorable shift in the levels of leptin and adiponectin." (PMID 33531076, 2021). "This activation of the aldose reductase–fructokinase pathway may lead to increased endogenous production of fructose and enhanced leptin resistance, both of which are implicated in insulin resistance." (PMID 34959961, 2021). "High leptin increases the synthesis of pro-inflammatory cytokines, promotes the development of insulin resistance, and predisposes the patient to metabolic and vascular complications, while low leptin may decrease the rate of PCTS." (PMID 34362176, 2021). "Furthermore, mice deficient of leptin have increased appetite, weight gain, insulin resistance and diabetes, conditions that can be improved with leptin therapy." (PMID 34421908, 2021). "Cardiovascular risk factors, leptin, ghrelin, and insulin resistance score values were assessed." (PMID 34829886, 2021). "In addition, leptin has been reflected to have a pathogenic role in hepatic insulin resistance and/or a failure of the antisteatotic actions." (PMID 34209386, 2021). "In addition, alteration in the relationship between leptin and adiponectin ratio has been shown to be associated with insulin resistance, and in the development of atherosclerosis." (PMID 33572702, 2021). "In the present study, the positive effect of LDAT via PPAR and AMPK effects on insulin resistance may cause the decrease in leptin and resistin levels and the increase in adiponectin levels." (PMID 33641315, 2021). "In our study, weight loss resulted in a tendency to lower leptin and insulin resistance." (PMID 34578973, 2021). "The LAR has recently been proposed as a reliable marker to predict insulin resistance and vascular risk in healthy adults: when an adipocyte became hypertrophic, it tends to increase the secretion of leptin relative to adiponectin, increasing the ratio between these two adipokines." (PMID 34649266, 2021). "FABP-4 and leptin are hormonal bioactive molecules secreted by adipose tissue that control energy balance, have been linked to metabolic and inflammatory pathways, and are associated with the development of insulin resistance and atherosclerosis." (PMID 34312731, 2021). "Indeed, it is well-known that ob/ob mice, which carry a homozygous mutation in the leptin gene that protect it from binding to its receptor, are susceptible to insulin resistance and T2D, thus being predisposed to metabolic features resembling NAFLD." (PMID 32046285, 2020). "However, only leptin was identified as a risk factor for the occurrence of insulin resistance in our study population, indicating the possible association of hyperleptinemia with insulin resistance independently of age, gender, and body constitution." (PMID 32092909, 2020). "It was also found that “Inactive & Sedentary LS”, high BF%, insulin resistance, and ultra-sensitive C-reactive protein were associated with the concentrations of proinflammatory biomarkers of tumor necrosis factor-α, interleukin-6, and leptin." (PMID 32694929, 2020). "In PCOS patients, high leptin concentrations are associated with insulin resistance and glucose intolerance, thus it could be used as indicator of metabolic disorders." (PMID 32545404, 2020). "The elevated leptin levels detected in our cohort likely largely reflects the greater adiposity observed, and an associated reduction in circulating adiponectin can potentially reflect insulin resistance." (PMID 32290749, 2020). "Reports show that dietary patterns are associated with adiponectin, leptin, and insulin resistance." (PMID 32944252, 2020). "High leptin levels are associated with insulin resistance and development of T2DM." (PMID 32130282, 2020).
Insulin resistance (continued). "Our results showed that increased leptin levels may be associated with insulin resistance because leptin levels were positively correlated with fasting serum insulin levels and HOMA‐IR index and negatively with QUICKI." (PMID 31914480, 2020). "Similar, glucocorticoids increase leptin mRNA and plasma leptin levels, but as they cause insulin resistance and hyperinsulinemia, the effect of glucocorticoids on leptin levels may be indirect." (PMID 32655492, 2020). "Whether associations between leptin or insulin resistance biomarkers and CRC risk differ by molecular subtypes has, to our knowledge, not been investigated." (PMID 32210264, 2020). "In this study, high levels of leptin were associated with increased BMI and insulin resistance." (PMID 33489589, 2020). "Further, insulin resistance mediated the association between leptin and incident type 2 diabetes." (PMID 32131811, 2020). "Our findings of an inverse association of adiponectin with incident type 2 diabetes and a positive association of leptin with incident type 2 diabetes mediated through insulin resistance corroborate findings from cross-sectional studies while adding a prospective/longitudinal element." (PMID 32131811, 2020). "Interactions between macrophages and adipocytes are early molecular factors influencing adipose tissue (AT) dysfunction, resulting in high leptin, low adiponectin circulating levels and low-grade metaflammation, leading to insulin resistance (IR) with increased cardiovascular risk." (PMID 32272872, 2020). "On the other hand, adiponectin, leptin, and resistin are associated with insulin resistance." (PMID 33292449, 2020). "A strong association has been reported between leptin and insulin resistance in the obese group." (PMID 30763324, 2019). "Moreover, lower ghrelin and higher leptin levels are associated with poorer regulation of blood glucose regulation, insulin resistance, and lower metabolic flexibility." (PMID 31466276, 2019). "Leptin-deficient mice (ob/ob) exhibit morbid obesity and insulin resistance." (PMID 31882890, 2019). "Leptin loss of function is associated with hyperphagia, rapid weight gain, and insulin resistance." (PMID 31824900, 2019). "Such chronic, low-grade inflammation both within the hypothalamus and in periphery, may contribute to the C57BL/6J strain’s inherent predisposition to insulin resistance and the associated leptin-impaired response to HFD3." (PMID 31873127, 2019). "We demonstrated that the consumption of RED extract restored the adipocyte profile to that found in the control diet group, abolishing adiponectin and leptin resistance, and dampening the overexpression of all the genes associated with the development of insulin resistance." (PMID 31337415, 2019). "In addition, by reducing the release of leptin, irisin reduces the proinflammatory activation of the entire system and thus reduces the risk of the development of insulin resistance." (PMID 31438646, 2019). "It is also suggested that inhibitory interplay between leptin and insulin signaling in the hypothalamus could have a causal role in the onset and the progression of hypothalamic insulin resistance." (PMID 30906281, 2019). "Moreover, it has been widely studied in leptin-deficient obese mice and linked to insulin resistance and diabetes, as well as to neurodegeneration in both mice and humans." (PMID 31766143, 2019). "The cardiometabolic risk markers (glucose, lipids, insulin, the insulin resistance/sensitivity indexes, leptin and Hcy) studied according to the n-6/n-3 classification, confirm that this vegetarian population exhibits a low cardiometabolic risk, in agreement with other authors." (PMID 31330792, 2019). "HP infection has also been recognized to be the causal factor of insulin resistance (IR), chronic low-grade systemic inflammation, the inhibition white adipose tissue to release leptin and gastrointestinal flora dysbiota, which are the causal factors of NAFLD25." (PMID 30890750, 2019).